ABHD16B (abhydrolase domain containing 16B)
Description:
Hydrolyzes the sn-1 position of glycerophospholipids with high specificity towards phosphatidylserine (PS), PS-PLA1 enzyme. Also hydrolyzes the acyl chain of glycerolipids with a preference for the monoacylglycerol (MAG) 1-acylglycerol, MAG lipase. Plays a regulatory role in cellular lipid homeostasis by modulating genes involved in neutral lipid degradation and in phospholipid synthesis and composition.
Synonyms: C20orf135; dJ591C20.1
Tractability: No criterion of Open Targets' tractability assessment is met for any kind of drug.
Gene: Protein-coding gene on chromosome 20 (63,861,498 to 63,862,988, forward strand). Ensembl gene ENSG00000183260.
Subcellular location (Human Protein Atlas): Nucleoplasm
Gene Ontology:
Molecular function: monoacylglycerol lipase activity; phospholipase activity; phospholipase A1 activity
Biological process: monoacylglycerol catabolic process; phosphatidylserine catabolic process
Cellular component: nucleoplasm
Genetic constraint (gnomAD): Loss-of-function variants: 18 observed, 10.57 expected, observed/expected ratio (o/e) 1.7, 90% interval 1.13 to 1.96. The synonymous counts are far from expectation, so gnomAD's model fits this gene poorly and the ratio says little. Missense variants: 763 observed, 582.63 expected, observed/expected ratio (o/e) 1.31, 90% interval 1.23 to 1.39. Synonymous variants: 374 observed, 260.77 expected, observed/expected ratio (o/e) 1.43, 90% interval 1.32 to 1.56.
Homologues: Orthologues: chimpanzee ABHD16B (99% identical), macaque ABHD16B (96% identical), pig ABHD16B (87% identical), guinea pig ABHD16B (85% identical), mouse Abhd16b (85% identical), rat Abhd16b (84% identical), dog ABHD16B (67% identical), Drosophila melanogaster CG1309 (33% identical), Caenorhabditis elegans F37A4.1 (29% identical), zebrafish abhd12 (12% identical), Caenorhabditis elegans F01D5.7 (8% identical), Caenorhabditis elegans F01D5.8 (7% identical). Paralogues in human: ABHD16A (55% identical), ABHD12B (14% identical), ABHD12 (11% identical), ABHD17A (10% identical), ABHD17B (10% identical), ABHD17C (10% identical), ABHD13 (9% identical).
Diseases named in the same sentence as ABHD16B in open-access papers:
ABHD16B is named in the same sentence as 5 diseases in open-access papers, as found by Europe PMC text mining. Sharing a sentence is not in itself a finding about the gene and the disease. The quoted sentences say what the papers report.
infertile (2 papers, 2020 to 2022). "In addition, aberrant methylation patterns of ABHD16B have been shown to be associated with infertility in men." (PMID 31963602, 2020). "The methylation of ABHD16B was reported to be associated with chronic obstructive pulmonary disease (COPD) and aberrant methylation patterns were identified in infertile man." (PMID 31963602, 2020).
male infertility (2 papers, 2020 to 2022). The inability of the male to effect fertilization of an ovum after a specified period of unprotected intercourse. "We have identified a nonsense mutation in the bovine ABHD16B gene as a potential causative protein-altering variant for male infertility in Holstein cattle." (PMID 31963602, 2020). "Recently it was shown that a specific form of male infertility in Holstein cattle was caused by a nonsense variant in the α/β-hydrolase domain-containing 16B (ABHD16B) gene resulting in a protein truncation at amino acid position 218 (p.218Q*) and loss of function." (PMID 35887122, 2022).
melanoma (1 paper, 2021). A malignant, usually aggressive tumor composed of atypical, neoplastic melanocytes. "In bone metastatic melanoma, AL118506.1 (antisense to abhydrolase domain containing 16B) participates in the ceRNA network of has-miR-27b-3p/AL118506.1/THBS2, which has great utility in predicting survival and metastasis of melanoma." (PMID 34966747, 2021).
ABHD16B also shares sentences with these, for which no sentence is quoted: cancer (1 paper); chronic obstructive pulmonary disease (1).